Y_RNA (Y RNA )
Gene: Miscellaneous RNA gene on chromosome 6 (135,474,504 to 135,474,609, reverse strand). Ensembl gene ENSG00000201012.
Homologues: Orthologues: chimpanzee Y_RNA (100% identical), macaque Y_RNA (96% identical), guinea pig Y_RNA (86% identical), mouse Gm22199 (69% identical). Paralogues in human: Y_RNA (81% identical), Y_RNA (80% identical), RNY1P2 (79% identical), Y_RNA (79% identical), Y_RNA (78% identical), Y_RNA (77% identical), Y_RNA (76% identical), RNY1 (75% identical), RNY1P7 (75% identical), Y_RNA (75% identical), RNY1P11 (74% identical), Y_RNA (74% identical), and 90 more.